INS (insulin)
Diseases named in the same sentence as INS in open-access papers (continued):
Sharing a sentence is not in itself a finding about the gene and the disease.
diabetes (continued). "Both scores can be criticised, and in particular the NAFLD-FLS includes a large number of correlated items as the metabolic syndrome is included, as well as diabetes and insulin, and also both AST and AST/ALT." (PMID 20529259, 2010). "Comprehensive diabetes treatment satisfaction instruments include the Insulin Delivery System Rating Questionnaire (IDSRQ) and the Pramlintide Treatment Satisfaction Questionnaire (PRAM-TSQ)." (PMID 20334647, 2010). "In that situation diabetes-prone sand rats experienced 33% greater feed efficiency and became insulin resistant, eventually storing more energy as body fat per calorie consumed than the resistant strain." (PMID 20398338, 2010). "Advise and teach women with insulin treated diabetes about the risks of hypoglycemia and how to prevent it, particularly during the night and during the sleeping hours." (PMID 20416099, 2010). "Berberine, identified from the traditional herb Hydrastis canadensis or Coptis chinensis which has been used for treating diabetes in China for more than 1400 years, has recently been shown to have glucose lowering, insulin sensitizing and incretin actions." (PMID 20735814, 2010). "This review discusses diabetes management focusing on the latest insulin analogues, alternative insulin delivery systems and the artificial pancreas." (PMID 20589066, 2010). "Rosiglitazone (RSG), developed for the treatment of type 2 diabetes mellitus, is known to have potent effects on carbohydrate and lipid metabolism leading to the improvement of insulin sensitivity in target tissues." (PMID 20953342, 2010). "The effects of crude polysaccharide from Purslane (CPP) on body weight (bw), blood glucose, total cholesterol (TC), high-density lipoprotein cholesterol (HDL-c), triglyceride (TG) and serum insulin levels were studied in diabetes mellitus mice." (PMID 19399226, 2009). "We then use the Browse command to display the contents of this dataset, locate the row containing OMIM entry 222100, "Diabetes Mellitus, Insulin-Dependent, IDDM", and select it by shift-clicking on it." (PMID 19728881, 2009). "Two patients developed iatrogenic diabetes and were discharged on subcutaneous insulin regimens for the maintenance of normoglycemia." (PMID 20049337, 2009). "Answer: The goal of insulin administration in patients with diabetes is to mimic normal physiologic secretion of insulin to control both fasting plasma glucose (FPG) and postprandial glucose (PPG) levels." (PMID 19573240, 2009). "Diabetes Mellitus is a chronic disease and many patients of which require frequent subcutaneous insulin injection to maintain proper blood glucose levels." (PMID 19642985, 2009). "The diabetes mellitus in Alström syndrome is the result of tissue resistance to the actions of insulin, as demonstrated by elevated plasma insulin levels and glucose intolerance, findings often present in childhood." (PMID 21274310, 2009). "Alloxan is a type of toxic glucose analogue that selectively destroys insulin-producing pancreatic β-cells upon consumption, leading to the development of insulin-dependent diabetes mellitus." (PMID 19865517, 2009). "Managing diabetes in patients with end-stage renal disease is often problematic, because renal failure interferes with the metabolism of glucose and insulin with wide fluctuations in the daily blood glucose profile." (PMID 19946579, 2009). "Classical non-insulin antihyperglycemic drugs currently approved for the treatment of type 2 diabetes mellitus (T2DM) comprise five groups: biguanides, sulfonylureas, meglitinides, glitazones and alpha-glucosidase inhibitors." (PMID 19619327, 2009). "The patients who reached this target had a shorter diabetes duration, lower HbA1c and needed less insulin, suggesting that it is easier to get optimal glycaemic control with BIAsp 30 when prescribing this insulin earlier." (PMID 19210701, 2009).
diabetes (continued). "It appears as though PUFA from marine sources potentially contribute to favourable modifications of diabetes-related parameters, possibly by increasing insulin sensitivity, decreasing inflammatory mediators, or altering lipid metabolism in lean adults." (PMID 19664246, 2009). "Once this has occurred, it is easy to envisage a vicious cycle resulting in progressive deterioration of insulin secretion and elevation of plasma FFAs culminating in glucose intolerance and overt diabetes." (PMID 19945403, 2009). "That is, as reviewed by Jiang and Zhang, the absolute levels of glucagon or the ratios of glucagon to insulin are often elevated in various forms of diabetes in both animal and human subjects." (PMID 19943948, 2009). "The hospital-based diabetes clinic should treat patients with case of complications and with complex insulin therapy schemes." (PMID 19624848, 2009). "Insulin resistance, as indicated by the HOMA2-IR index or the inverse of the Matsuda insulin sensitivity index, was greatest among those with diabetes, intermediate among those with IFG and lowest among those with NFG." (PMID 19476649, 2009). "On average, respondents had been diagnosed with diabetes for 23.5 years (SD 14.0, range 3 - 58) and had used insulin pumps for 2.8 years (SD 1.6, range 1 - 6)." (PMID 21821504, 2009). "HD patients develop diabetes 7 times more often than control age-matched subjects and the decreased insulin secretion seems to be a possible explanation." (PMID 27713238, 2009). "Fear of the complications of insulin therapy, particularly hypoglycemia, by both patients and health care workers, is one of the major barriers to implementing intensification of diabetes management." (PMID 19426530, 2009). "Thus, a higher rate of insulin transcription in persons with class I homozygous genotypes may genetically predispose them to diabetes by providing an increased endogenous source of dsRNA-like molecules that contribute to 2′5′AS activation in beta cells, particularly during virus infection." (PMID 19888425, 2009). "Our study yielded systemic in-vivo evidence in different structural levels to explain how diabetes aggravate myocardial I/R injury and reveal the role of insulin signaling." (PMID 19706162, 2009). "Within diabetes references, two subcategories encompass the majority of thereferences, namely those related to proinsulin/insulin and glutamic aciddecarboxilase (GAD), respectively." (PMID 19774228, 2009). "The greater overall satisfaction with diabetes medication that we report for BIAsp 30 compared with the previous insulin therapy is thus a clear indication of improvements in many aspects of patients’ lives." (PMID 19504715, 2009). "At this point, diabetes mellitus was considered as the result of resistance to the action of insulin." (PMID 19128470, 2009). "As a consequence, the blood glucose levels of the insulin treated mice were lower than the untreated diabetics, although their blood glucose levels were still elevated above 250 mg/dl." (PMID 19936028, 2009). "As it happens in type 2 diabetes mellitus (DM2) and in metabolic syndrome (MS), when dysglycemia is present, GDM is associated to both insulin resistance and impaired insulin secretion." (PMID 19825195, 2009). "Insulin treatment in diabetes showed improvement of contractile function as well as partially increased Akt phosphorylation and GLUT 4 protein levels." (PMID 19706162, 2009). "Here we report on a rare case of secondary diabetes in glycogen storage disease type III that has been successfully managed with insulin." (PMID 19829878, 2009). "The intervention was insulin therapy added to any diabetes control regimen with oral agents or exenatide." (PMID 19573240, 2009). "On the other hand, serum insulin levels in patients with diabetes can be variable depending on the length of time with the disease, the type of therapy and the presence of differing degrees of insulin resistance." (PMID 19828038, 2009).
diabetes (continued). "Tattersall argues patients must have the freedom and approval from their providers to change their treatment, specifically patients with diabetes should feel empowered to make adjustments in their insulin dose to match their food choices." (PMID 19232113, 2009). "Diabetes mellitus is a common name for a group of metabolic diseases characterized by hyperglycemia resulting from defects in insulin secretion and/or action." (PMID 19463182, 2009). "Insulin glargine is a long-acting insulin analogue, authorised in the European Union (EU) as Lantus and Optisulin, for the treatment of adults, adolescents and children aged six years or above with diabetes, when treatment with insulin is required." (PMID 24966880, 2009). "PS-HOSO supplementation to diabetes-prone gerbils counteracts the increase in body weight and epididymal fat accumulation, and also results in a drop in circulating insulin levels." (PMID 19822001, 2009). "Decline in insulin action is a metabolic feature of aging and is involved in the development of age-related diseases including Type 2 Diabetes Mellitus (T2DM) and Alzheimer's disease (AD)." (PMID 19623253, 2009). "Because of a growing interest to treat type-II diabetes with gastric bypass surgery, the rapid and long-term improvement of insulin sensitivity and the reduction of diabetes in subjects post surgery has become a primary axis of interest." (PMID 19936240, 2009). "Under pathological conditions such as diabetes and myocardial ischemia, insulin signal transduction pathways, such as phosphatidylinositol 3-kinase/protein kinase B (Akt) signaling, are clearly modified." (PMID 19706162, 2009). "Diabetes mellitus was treated with insulin, using a combination of rapid-acting analogues and lente insulin and hypoparathyroidism with 1,25-dihydroxycholecalciferol and ketosteril (amino acids plus calcium)." (PMID 19946579, 2009). "In conclusion, the p38δ-PKD pathway integrates regulation of the insulin secretory capacity and survival of pancreatic β cells, pointing to a pivotal role for this pathway in the development of overt diabetes mellitus." (PMID 19135240, 2009). "Conventional drugs treat diabetes by improving insulin sensitivity, increasing insulin production and/or decreasing the amount of glucose in blood." (PMID 19523223, 2009). "We first demonstrate that a lack of serotonin in β-cells of transgenic mice leads to reduced insulin secretion and diabetes mellitus and that pharmacological replenishment of serotonin rescues insulin secretion in these mice." (PMID 19859528, 2009). "In fact, insulin is used as the sole drug in clinical practice to deal with blood hyperglycemia in diabetes." (PMID 19943948, 2009). "Type 2 diabetes mellitus (T2DM) is characterized by hyperglycemia that can occur through mechanisms such as impaired insulin secretion, insulin resistance in peripheral tissues and increased glucose output by liver." (PMID 19228405, 2009). "In type 1 diabetes (insulin-dependent diabetes mellitus (IDDM)), this results from an absolute deficiency of insulin secretion." (PMID 19936237, 2009). "Reduced insulin-mediated glucose disposal in muscle and impaired suppression of hepatic glucose production by insulin are common metabolic features of both obesity and type 2 diabetes mellitus (T2DM)." (PMID 19656356, 2009). "Both impaired insulin sensitivity and pancreatic beta-cell dysfunction play central roles in the pathogenesis of type 2 diabetes mellitus." (PMID 19476649, 2009). "The relatives of respondents had diabetes for a mean of seven years and were treated with diet alone (18%), tablets (60%) or insulin (22%)." (PMID 20003280, 2009). "In comparison, in the USA, around 30% of adults with diabetes are using insulin, either alone or combined with oral medication." (PMID 19602220, 2009).
diabetes (continued). "Pathways important for the function, growth and development of pancreatic β-cells provide obvious drug targets and are already being used, since defects in insulin secretion play a central role in diabetes." (PMID 19794883, 2009). "Three patients developed iatrogenic diabetes and were discharged home on subcutaneous insulin regimens." (PMID 20049337, 2009). "Insulin injections, glucose-lowering drugs and lifestyle changes, such as exercise, weight control and diet therapy, are recommended for treating diabetes." (PMID 19523223, 2009). "Apoptosis of the insulin producing β-cells and the decline in β-cell mass is a major mechanism of the progression of diabetes." (PMID 19197367, 2009). "One grade 2 patient with a high HOMA before surgery (2.93) developed diabetes at 22.4 years, with high fasting plasma insulin concentrations (27 mIU/L); treatment with Metformine and Glimepiride normalised the blood glucose concentration." (PMID 19341477, 2009). "This is supported by our findings that GLP-1 analogue group, when compared to insulin users, had significantly more positive impacts for Diabetes Management, the domain which captures the impact of hypoglycaemia, as well as in the Compliance domain." (PMID 19740444, 2009). "Factors associated with increased costs included insurance type, geographical region, diabetes-related comorbidities, and insulin therapy." (PMID 19566952, 2009). "Our study provided systemic in-vivo evidence in different structural levels to explain how diabetes can aggravate myocardial I/R injury and revealed the role of insulin signaling." (PMID 19706162, 2009). "Diabetes is generally considered as a peripheral disease characteristic of dysfunction of such peripheral glucose-insulin-glucagon (GIG) interactions." (PMID 19943948, 2009). "The main purpose of this study was to determine the effect of insulin treatment in STZ-induced diabetes on skeletal muscle sorbitol values." (PMID 20016800, 2009). "They had overt diabetes at the age of 14 and 21 weeks, with persistence of some insulin secretion at 14 weeks, but almost undetectable insulin level at 21 weeks." (PMID 20030821, 2009). "The pooled adjusted RR for recurrent falls was 2.74 (CI, 1.85 to 4.07) when older women with insulin-treated diabetes were compared to controls." (PMID 19127292, 2009). "At this juncture, it is pertinent to note that imatinib therapy in CML patients with diabetes improves insulin sensitivity and fasting blood glucose levels." (PMID 19693287, 2009). "The ability to accurately monitor blood glucose results with self monitoring of blood glucose (SMBG) is pivotal to the success of managing and controlling blood glucose levels in people with diabetes on insulin." (PMID 19426530, 2009). "Transition to insulin therapy is one of the obstacles in diabetes management, because of barriers of both patient and health care providers." (PMID 19508712, 2009). "This form of diabetes usually begins with insulin insensitivity, a condition in which muscle, liver and fat cells do not respond to insulin properly." (PMID 19523223, 2009). "Following this patient-centered approach, we report here on pilot testing of the Internet-based virtual clinic for patients using insulin pumps to manage their diabetes." (PMID 21821504, 2009). "The mice exhibited classic signs of diabetes—elevated blood glucose and decreased insulin secretion." (PMID 20076734, 2009). "Increased blood glucose and decreased body weight observed during diabetes is similar with previous reports as a result of the marked destruction of insulin secreting pancreatic islet β-cells by streptozotocin." (PMID 19903331, 2009). "Considering the impact of obesity on diabetes, along with weight gain that generally accompanies the use of insulin, insulin secretagogues, and insulin sensitizers, interventions with favorable effects on weight are likely to become increasingly important." (PMID 19619327, 2009).
diabetes (continued). "The diabetes was managed by subcutaneous insulin therapy based on eight-hourly blood sugar level estimation." (PMID 20368850, 2009). "If you have diabetes and come in and are prepared for insulin, if that is what you now need, then that is very health promoting." (PMID 19845948, 2009). "In 2005, Copelli compared DM1 patients submitted to PTA with DM1 patients kept under intensive insulin therapy (control group), similar in age, gender, diabetes type, and use of statins and anti-hypertensive drugs." (PMID 19825148, 2009). "We have previously established that insulin autoantibodies (E-IAA) predict early diabetes onset delineating an early phenotypic check point (window 1) in disease pathogenesis." (PMID 19799787, 2009). "While serotonin (5-HT) co-localization with insulin in granules of pancreatic β-cells was demonstrated more than three decades ago, its physiological role in the etiology of diabetes is still unclear." (PMID 19859528, 2009). "We evaluated the association of serum selenium, measured by inductively coupled plasma-dynamic reaction cell-mass spectrometry, and diabetes, defined as a self-report of current use of hypoglycemic agents or insulin or as fasting plasma glucose ≥ 126 mg/dL." (PMID 19750106, 2009). "The ultimate goal of the DreamTel project is to develop a process for initiating insulin therapy in the community setting including intensification of diabetes management in a culturally appropriate manner." (PMID 19426530, 2009). "Diabetes is an inflammatory condition in which up-regulation of inflammatory markers such as tumor necrosis factor (TNF)-α leads to impaired insulin signaling." (PMID 19825152, 2009). "There is an inverse relation between plasma testosterone and insulin sensitivity, type 2 diabetes mellitus and HbA1c concentrations." (PMID 19327165, 2009). "Patients who reached the HbA1c target (< 7%) had shorter diabetes duration, lower HbA1c at baseline and needed less insulin." (PMID 19210701, 2009). "Subjects with diabetes had insulin and C-peptide responses that were intermediate between the NFG and IFG groups." (PMID 19476649, 2009). "The interrelationship of the effects of SERCA2a and insulin pathway appear to be beneficial to the myocardium in pathological conditions such as diabetes." (PMID 19649297, 2009). "This is especially important for the correlation between diabetes and cell death in insulin-producing β cells." (PMID 19826422, 2009). "In type 2 diabetes (non-insulin-dependent diabetes mellitus (NIDDM)) both insulin resistance of target organs and inadequate insulin secretion cause hyperglycemia." (PMID 19936237, 2009). "The TZDs are insulin-sensitizing drugs that improve insulin sensitivity in insulin-resistant states such as type 2 diabetes mellitus and obesity." (PMID 19587804, 2009). "Two patients had diabetes mellitus, and all three had a glucose-to-insulin ratio (GIR) less than 4.5 indicating insulin resistance." (PMID 19128470, 2009). "We report a rare case of secondary diabetes mellitus in a patient with glycogen storage disease type III managed with insulin." (PMID 19829878, 2009). "Although, there have been major advances in the control of hyperglycemia through dietary changes, hypoglycemic agents, insulin, and islet transplantation, the long-term complications of diabetes, such as cataract, remain serious problems." (PMID 19898641, 2009). "The available therapies for diabetes include insulin and many oral hypoglycemic agents, such as biguanids and sulfonylureas." (PMID 19943967, 2009). "There were also substantial reductions in cumulative incidence and time to onset of all diabetes-related complications with immediate versus delayed insulin initiation." (PMID 19804622, 2009). "Since extracellular glucose diffuses into the lens uncontrolled by the hormone insulin, the lens is one of the body parts most affected in diabetes." (PMID 19898641, 2009).